IL1B (interleukin 1 beta)
Diseases named in the same sentence as IL1B in open-access papers (continued):
Sharing a sentence is not in itself a finding about the gene and the disease.
lung carcinoma (continued). "Since it has previously been reported that upon activation, NLRP3 inflammasome induces proteolytic cleavage and conversion of pro-IL-1β to IL-1β and IL-1β, in turn, promotes proliferation and migration of the lung cancer cells as well as tumor growth and angiogenesis." (PMID 34094030, 2021). "On the other hand, the accumulation of IL-1β could form a positive feedback loop to promote lung cancer cells to further secrete cytokines such as VEGF and MMPs." (PMID 34055197, 2021). "Therefore, in vivo experiments also revealed that inhibiting the IL-1β/NF-κB pathway was one of the important mechanisms for the FZQX prescription in preventing lung cancer progression via regulating MDSCs." (PMID 34055197, 2021). "This link of IL-1β to lung cancer has been recently clinically tested, with fascinating results." (PMID 33494181, 2021). "However, genetic instruments for IL-1Ra which is drugged by anakinra were associated with lung cancer/LUAD only after adjustment for the genetically predicted effects of IL-1α and IL-1β in this study." (PMID 34475499, 2021). "Of these 127 cis-pQTLs (including an overlap cis-pQLT of rs61335305 for both IL-1β and IL-1Ra, which was only used for robust multivariable MR analyses), we excluded 23 palindromic and 47 incompatible instruments concerning those for lung cancer in ILCCO." (PMID 34475499, 2021). "In this context, the present study demonstrates a previously unknown dual IL-1β-triggered mechanism of TF expression in lung cancer cells and thus defines upstream targets for pharmacotherapeutic intervention to block the formation of protumorigenic TF." (PMID 34205482, 2021). "In addition, AZD6244 treatment of human lung cancer cells showed a consistent upregulation of Th17-associated genes (TGF-β, IL6, IL23, IL17, IL22, IL1b, and RORγt)." (PMID 33972557, 2021). "Evidences indicate that increase of IL-6 was not only occurred in liver ablation, researches focus on lung cancer, including primary lung cancer and pulmonary metastases demonstrated that serum IL-8, IL-1β, IL-6, IL-10, IL-12 and TNF-α were significantly raised after radiofrequency thermal ablation." (PMID 32847533, 2020). "Results from CANTOS suggest that canakinumab‐mediated blockage of IL‐1β activity protects against the development of lung cancer, although the mechanism involved remains unclear." (PMID 32770571, 2020). "CANTOS (Canakinumab Anti-inflammatory Thrombosis Outcomes Study) showed that canakinumab, a human monoclonal antibody targeting IL-1β, reduced the incidence of lung cancer in patients with atherosclerosis, highlighting it as a promising approach to prevent lung cancer." (PMID 32703253, 2020). "Next, we investigated whether L-MP-induced IL-1β produced by macrophages could be utilized for human lung cancer." (PMID 31649305, 2020). "Our results show that tumor necrosis factor-α (TNF-α) and IL-1β upregulated Oct4 expression in lung cancer cells, which may in turn transcriptionally activated M-CSF expression." (PMID 32487125, 2020). "These exploratory results suggest that IL‐1β neutralization may contribute importantly to intercepting the health trajectory of lung cancer patients and warrant further confirmation in independent studies." (PMID 32770571, 2020). "Using the Lewis lung cancer model, we found that the injection of L-MPs (Lewis) into the tumors resulted in accelerated tumor growth in the muscle and shortened the survival time of the mice, but these changes were blocked by an IL-1β neutralizing antibody." (PMID 31649305, 2020). "Particularly noteworthy, the Canakinumab Anti-inflammatory Thrombosis Outcomes Study (CANTOS) revealed that IL-1β inhibition with the neutralizing antibody canakinumab decreases both the incidence and mortality of lung cancer in patients with atherosclerosis co-morbidities." (PMID 31941995, 2020).
lung carcinoma (continued). "Our results showing upregulation of Oct4 in lung cancer cells either by coculture with macrophages or with TNF-α or IL-1β provide supports for the acquired cancer stem cell hypothesis." (PMID 32487125, 2020). "In sum, our results showed that, tumor-derived exosomal TRIM59 converts macrophages to tumor-promoting functions of macrophages via regulating ABHD5 proteasomal degradation, to activate NLRP3 inflammasome signaling pathway to promote lung cancer progression by IL-1β secretion." (PMID 32867817, 2020). "Collectively, these data indicate that tumor-derived exosomal TRIM59 converts macrophages to tumor-promoting functions of macrophages via regulating ABHD5 proteasomal degradation, to activate NLRP3 inflammasome signaling pathway to promote lung cancer progression by IL-1β secretion." (PMID 32867817, 2020). "Notably, L-MPs from other lung cancer cell lines (murine Lewis or human A549 and H460 cells lines) also induced macrophages to upregulate IL-1β, but the MPs isolated from other tumor cells, healthy murine cells or human blood cells did not have such an effect." (PMID 31649305, 2020). "Excitingly, a recent phase three clinical trial (CANTOS) demonstrated that an inhibitory antibody targeting IL-1β (canakinumab) could significantly reduce the incidence and mortality of lung cancer." (PMID 31231372, 2019). "Interestingly, IL1B is part of this inflammation-related gene module, and inhibition of IL1B has recently been shown to reduce lung cancer incidence." (PMID 31015447, 2019). "Similar to the studies describing a reduction of the IL-8 levels in lung cancer cells co-treated with IL-1β and Phlor (30–100 μM), we showed a significant decrease of IL-8 level at 50 μM Phlor, and a non-significant tendency to reduce its biosynthesis at 10 μM." (PMID 31130634, 2019). "Since IL-1β has been linked to airway inflammation, it will be of interest to know if the high CRP levels in the CANTOS trial at baseline were associated with an incidence of COPD, known to increase lung cancer risk." (PMID 30832375, 2019). "During a randomized, double-blinded, placebo-controlled trial of patients with lung cancers and atherosclerosis, researchers found that canakinumab could significantly decrease lung cancer mortality by targeting the IL-1β innate immunity pathway." (PMID 31242947, 2019). "Initial evidence suggests that targeting the innate immunity pathway through IL-1β inhibition with canakinumab could significantly reduce incident lung cancer and lung cancer mortality in patients treated for atherosclerosis." (PMID 31416487, 2019). "Additionally, urethane-induced lung cancer mouse models, in which myeloid NF-κB was inhibited, displayed increased levels of IL-1β and cell proliferation." (PMID 32039025, 2019). "These factors help promote lung cancer pathogenesis, with one of the more intriguing recent clinical results being the observation that the IL-1β inhibitor canakinumab, in a trial assessing activity in reducing atherosclerosis, showed unexpected efficacy in reducing the incidence of lung cancer." (PMID 29945886, 2018). "Nanoparticles (NP) such as silica and asbestos may result in the overexpression of NLRP3 inflammasomes, and the secretion of caspase-1 and IL1β in the in vivo model of lung cancer." (PMID 30447690, 2018). "Interestingly, in an additional analysis of the data, the authors report separately that IL-1β inhibition also led to significant reductions in the incidence of lung cancer and lung cancer mortality." (PMID 29515457, 2018). "In addition, RUNX1 expression in both the MDSCs from the tumor tissue of lung cancer patients and MDSCs induced with GM-CSF and IL-1β was decreased compared with cells of the same phenotype from adjacent tissue and PBMCs, respectively (P < 0.05)." (PMID 29914443, 2018). "Interestingly, exploratory data from a randomized trial proposed that IL-1β inhibition results in decreased incidence of Lung cancer in patients with high CRP." (PMID 30365491, 2018).
lung carcinoma (continued). "Both IL-1β and IL-6 are well known to up-regulate the aromatase gene transcripts and its activity in several types of cells, including osteoblasts (IL-1β) and fibroblasts derived from lung cancer (IL-6)." (PMID 29039776, 2017). "Indeed, a previous study has demonstrated that M. pneumoniae infection induces proinflammatory cytokine expression in human lung carcinoma cell line (A549) including IL1β, IL6, IL8, and TNFα." (PMID 28553017, 2017). "Breast and lung cancer patients also found that could detect more high IL-1β levels compared to health adult." (PMID 29254155, 2017). "Previously, most of views thought that IL-1β could induce P38 MAPK activation in gastric adenocarcinoma, and pretreatment of cells with tangeretin could inhibit IL-1β-induced P38 MAPK in human lung carcinoma cells." (PMID 26980948, 2016). "According to our findings, cigarette smoking could possibly induce IL-1β in lung carcinoma and transactivate EGFR through CXCL1-CXCR2 axis." (PMID 26462152, 2015). "Interestingly, co-culturing lung cancer cells with macrophages resulted in increases of IL-1β and IL-6, which, in turn, stimulate lung cancer cells to induce SAA1/2 production." (PMID 28250368, 2014). "What is more, a significant correlation of TP with IL-1β (R = 0.514, p = 0.001) and IL-6 (R = 0.519, p = 0.002) was observed thus confirming our data from the animal model showing a potential novel effect of TP upregulation in the carcinoma of the lung." (PMID 24819505, 2014). "For example, myeloid cell derived IL-1β stimulates myeloid cell recruitment in vivo and pharmacological inhibition of IL-1β reduced the infiltration of myeloid cells into the tumor microenvironment and inhibited tumor progression in a lung cancer tumor model." (PMID 22938502, 2012). "Interestingly, receptor expression for IL-6 increased with time, while receptor expression for TNF-α and IL-1β decreased with time, in the case of lung cancer cells interacting with astrocytes." (PMID 23271367, 2012). "Accordingly, IL-1β is able to facilitate tumor progression in murine models of lung cancer." (PMID 18801189, 2008). "Future clinical trials should explore IL-1β inhibitors in combination with targeted therapies in molecularly defined subgroups, which have the potential to pave the way for more personalized and effective treatment strategies in lung cancer, ultimately improving patient outcomes." (PMID 40940992, 2025). "We then asked whether IL-1β activates pathways that lead to immune tolerance of lung cancer cells." (PMID 37985999, 2023). "Statistical significance was observed for IL-1b (p = 0.044), IL-2 (p = 0.040), IL-6 (p = 0.001), IL-10 (p = 0.008), IL-12p70 (p = 0.001), and TNF-alpha (p = 0.046), indicating that these inflammatory markers are significantly associated with the risk of lung cancer." (PMID 37373957, 2023). "Importantly, a retrospective analysis of the Canakinumab Anti-inflammatory Thrombosis Outcomes Study (CANTOS) showed that treatment with anti-IL-1β antibody, canakinumab, drastically reduced incidence and mortality of lung cancer in patients with prior myocardial infraction." (PMID 37985999, 2023). "Moreover, we found that IL-1β exposure also elevated PDL-1 levels in lung cancer cells." (PMID 37985999, 2023). "Furthermore, IL-1β presents an alternative mechanism in lung cancer development." (PMID 38067398, 2023). "Moreover, IL-1β blockade reduces the incidence and mortality of lung cancer." (PMID 37985999, 2023). "The activation of NLRP3 inflammasome could promote the proliferation and migration of lung adenocarcinoma A549 cells by mediating the release of IL-18 and IL-1β through the caspase-1 dependent pyroptosis pathway, while blocking IL-18 and IL-1β signaling could inhibit the progression of lung cancer." (PMID 37194012, 2023).
lung carcinoma (continued). "In a randomized controlled trial of an anti-IL-1β monoclonal antibody (CANTOS study), originally designed as a secondary prevention trial to reduce cardiovascular events, serum CRP and IL-6 were found to be associated with lung cancer incidence and with time to cancer diagnosis." (PMID 35406394, 2022). "Canakinumab, a human monoclonal antibody against IL-1β, has been established for over a decade in the treatment of rheumatological conditions and other immunological diseases and recently has been shown to be efficacious in reducing lung cancer incidence in a dose-dependent manner." (PMID 36264639, 2022). "Moreover, a 2-gene signature (IL-1β/TGF-β1) is correlated with the OS of lung cancer patients." (PMID 33175182, 2021). "The CANTOS trial, which was a randomized control trial of canakinumab, a monoclonal antibody targeting IL-1β, demonstrated that inhibition of IL-1β decreased the rate of recurrent cardiovascular events and that blocking IL-1β could decrease lung cancer incidence and mortality." (PMID 34858390, 2021). "Hence, it could be considered that the IL-1β/NF-κB signaling pathway was one of the key pathways of the FZQX prescription regulating MDSCs to inhibit lung cancer progression." (PMID 34055197, 2021). "NLRP3 inflammasome activation-induced IL-1β and IL-18 in lung cancer may work through mechanisms other than the caspase-1 pathway, indicating that NLRP3 inflammasome can mediate the release of IL-1β and IL-18 through caspase-1-dependent or -independent pathways." (PMID 33613533, 2020). "Thus, the elevated IL-1β concentration in TME could either derive directly from oncogenic lung cancer cells or eventually from another TAM population (i.e., infiltrated MoTAMs)." (PMID 30832375, 2019). "Additionally, published reports from the CANTOS trial suggested that targeting IL-1β could reduce the incidence of lung cancer and lung cancer mortality." (PMID 31346466, 2019). "Furthermore, we isolated F4/80+ TAMs from PBS- or HCQ-treated mice with orthotopic lung cancer, and we found that the M1-like molecules (Nos2, Ifng, IL12b,and IL1b) were up-regulated and the M2-like molecules (Arg1, Tgfb1, IL10, and Ido1) were down-regulated with HCQ treatment." (PMID 30373678, 2018). "Astrocytes have been shown to produce a wide variety of cytokines and growth factors; among them, it was suggested that IL-6, TNF-α and IL-1β may contribute to the development of brain metastasis by lung cancer cells, and IL-6, TGF-β and IGF-1 by breast cancer cells." (PMID 23271367, 2012). "The incidental finding from the CANTOS trial, where IL-1β inhibition with canakinumab reduced lung cancer incidence and mortality, prompted the CANOPY trials, which evaluated IL-1β blockade in NSCLC." (PMID 40940992, 2025). "During the lung cancer brain metastasis, lung cancer cells secrete IL-8, MIF, and PAI-1, which activate astrocytes and induce the expression of TNF-α, IL-1β, and IL-6, thereby promoting the proliferation of cancer cells." (PMID 41268299, 2025). "RES suppressed the inflammatory microenvironment, decrease the expressions of p‐NF‐ĸB, IL‐1β, IL‐8, and IL‐23, and inactivate the STAT3/VEGF signaling pathway, thereby reducing drug resistance in lung cancer cells." (PMID 40860906, 2025). "The mechanisms driving lung cancer due to fine PM are not primarily through increased genetic mutations but rather rely on altering the immune system, creating an inflammatory microenvironment, attracting macrophages to the lungs, and stimulating the release of IL-1β." (PMID 38605869, 2024). "We describe here the results of MAP3K8 knockdown in the A549 lung cancer cell line, the BEAS-2B epithelial cell line and normal human bronchial epithelial (NHBE) cells following IL-1β stimulation." (PMID 39030600, 2024). "The median IL-6, TNFα, IL-1β, and IFN-γ values were higher in lung cancer cases than in the subcohort." (PMID 38067398, 2023).
lung carcinoma (continued). "Overall MDR results show that smoking duration as the main effect and the interactions between IL1B htSNP and PPP1R13L SNP and POLR1G SNP and smoking duration play critical roles in the occurrence of lung cancer and lung squamous cell carcinoma." (PMID 37147350, 2023). "Nevertheless, the IL-1β induction of IDO1 and its product Kyn is likely to reduce the growth of lung cancer cells in vivo due to the ability of Kyn to blunt T-cells activity and allow for immune evasion." (PMID 37985999, 2023). "The study measured the concentration of IFN-γ, TNF-α, IL-1β, IL-2, IL-4, IL-6, IL-10, and IL-12p70, in venous blood and BALF of a total of 33 patients with lung cancer and 33 patients with benign lung diseases." (PMID 37373987, 2023). "IL-1β and PAK1 are known to increase migration and invasion in various cancer cells, including lung cancer, which is consistent with our results." (PMID 38188678, 2023). "High baseline levels of CRP and IL-6 trended toward shorter median time to lung cancer diagnosis, suggesting that IL-1β-inducible CRP and IL-6, similar to ctDNA at baseline, correlate positively with a more rapid progression to lung cancer diagnosis." (PMID 36074553, 2022). "For example, lung cancer microparticles (L-MPs) activated TLR3 and NLRP3 inflammasome, induced macrophages to release IL-1β, and thus promoted lung cancer development." (PMID 35413927, 2022). "Lung cancer-derived EVs induce NLRP3 activation in macrophages, thus providing a positive feedback loop to promote cancer progression via IL-1β secretion in mice." (PMID 35530309, 2022). "Several previous studies reported the prognostic value of a single immune-related gene in EPC or lung cancer, such as FGFR1, TNFRSF10B, and IL1B." (PMID 36147506, 2022). "By inhibiting IL-1β, HSP (100 μM) decreases COX-2 expression and its regulation in translation level in A549 lung cancer cell and PGE2 synthesis, indicating its anti-inflammatory and anti-cancer potential in human lung cancer cells." (PMID 35128104, 2022). "Overexpression of Snail1 in lung cancer cells shows increased production of inflammatory cytokines TNF-α, IL-1β, and IL-6 by regulating macrophage activation." (PMID 36159784, 2022). "Furthermore, IL1B is another key cytokine involved in inflammation and inflammasome activation; elevated levels of active IL1B contributed to intratumoral macrophage activation, accumulation of immunosuppressive myeloid cells, tumor growth, and lung cancer progression." (PMID 35884843, 2022). "Further investigation confirmed that the IL-1β/NF-κB signaling pathway was one of the key pathways for FZQX prescription involved in preventing recurrence and metastasis of lung cancer by regulating MDSCs." (PMID 34055197, 2021). "LIUS-downregulated innatomic genes were upregulated more than downregulated in proinflammatory cytokine IL-6 KO cells, IL-1β KO, and anti-inflammatory cytokine TGF-β-treated lung carcinoma cells." (PMID 33628851, 2021). "A study showed that Quercetin reduced the production of nickel-induced cytokines, such as IL-1β, IL-6, TNF-α, and IL-10, in lung cancer cell lines." (PMID 33918290, 2021). "MPE-Mφ showed relatively higher expression levels of M1 (IL-1β, IL-6, and CXCL10), M2 (CCL18 and IL-10), and pan-macrophage markers (CSF1 and PTPRC) compared to MDMs from lung cancer patients or HCs." (PMID 33175182, 2021). "LIUS-upregulated IGs were downregulated more than upregulated in proinflammatory cytokine TNF-α KO cells, IL-6 KO cells, IL-1β KO, and anti-inflammatory cytokine TGF-β-treated lung carcinoma cells." (PMID 33628851, 2021). "Here, we were able to more precisely perform late stage survival predictions by using only the two-gene signature of the M1 (IL-1β) and M2 (TGF-β1) genes directly from MPE-Mφ or lung cancer tissues." (PMID 33175182, 2021).